EGFR (epidermal growth factor receptor)
Diseases named in the same sentence as EGFR in open-access papers (continued):
Sharing a sentence is not in itself a finding about the gene and the disease.
lung cancer (continued). "For example, METTL3 could promote lung cancer tumor growth and invasion by boosting the translation of EGFR or TAZ transcripts independent of its catalytic activity." (PMID 36008805, 2022). "It is conceivable that blocking PD-1 in the EGFR-driven mouse model of lung cancer did not change the number of Tregs expressing high levels of CTLA-4, while combined dual ICIs may have a coordinated effect." (PMID 35935943, 2022). "Interestingly, miR-21 over-expression was exaggerated in EGFR gene mutant cases and suppressed by treating EGFR tyrosine kinase inhibitors in never-smoking lung cancer patients." (PMID 35885514, 2022). "However, EGFR inhibition may result in an activation of the compensatory pro-survival signaling in tumors, including antiapoptotic protein BCL2 upregulation in lung cancer cells." (PMID 36361596, 2022). "We speculated that increased IFN-γ during coculture with activated PBMC stimulated CXCL10 expression in EGFR-mutant lung cancer cell lines regardless of EGFR-TKI treatment; however, activated PBMC without coculture did not express CXCL10." (PMID 36612121, 2022). "More importantly, the expression of epidermal growth factor receptor (EGFR) could be represented as a negative feedback that is controlled by COX-2 in patients suffering from lung cancer by mediating the activation of several signaling cascades." (PMID 36339607, 2022). "The discovery of druggable targets such as epidermal growth factor receptor (EGFR), anaplastic lymphoma receptor tyrosine kinase (ALK), MET, ROS-1receptor tyrosine kinase and Kirsten rat sarcoma viral oncogene homolog (KRAS) open avenues for treating lung cancer." (PMID 35743687, 2022). "The CQDs were conjugated with a target molecule (Cetuximab) to facilitate CQDs-C225 labeling of HCC827 (lung cancer cell line, epidermal growth factor receptor (EGFR) over expression), H23 (lung cancer cell line, EGFR under expression), and HLF (normal lung cell line, EGFR under expression) cells." (PMID 35889495, 2022). "PD-L1-enhancing oncogenes, such as EGFR, ALK, MET, AKT, MYC, and CDK5, were not identified as hits in this study because KRAS mutations in lung cancer cell lines (H2009 and H460) could establish distinct PD-L1 regulatory axes." (PMID 36357569, 2022). "The present study evaluated patients with brain metastases from lung cancer not eligible for targeted drugs such as EGFR tyrosine kinase inhibitors, who initially received systemic therapy, the approach recommended by the institutional MDT for selected patients." (PMID 35020043, 2022). "Thus, the G12C and G12V alterations that are especially enriched in lung cancer are most commonly the result of smoking induced toxicity, rather than a single strong driving mutation such as ALK or EGFR." (PMID 36136862, 2022). "One such success story is the discovery of osimertinib, a third-generation EGFR TKI that targets activating mutations with or without the T790M gatekeeper mutation, which has significant clinical benefit in patients with non–small cell lung cancer (NSCLC) with activating mutations in EGFR." (PMID 36969743, 2022). "Likewise, in H1299 lung cancer cells, there was no increase in binding of EphA2 to the EGFR mutant when Ephexin1 was absent." (PMID 35668076, 2022). "However, the research related to the efficacy of EGFR-TKIs on the lung cancer patients of the coal-producing regions has not yet been reported." (PMID 35606799, 2022). "Using microvascular endothelial cells, lung cancer derived fibroblasts, and NSCLC tumor cells in the presence of in vivo tumor-derived hemodynamic flow and transport, we demonstrate that the TMES generates an in-vivo like biological state and predicts drug response to EGFR inhibitors." (PMID 33692370, 2021).
lung cancer (continued). "Previous studies found that SPP1 played a role in lung cancer escape and mediating macrophage polarization, while inhibiting SPP1 expression might overcome resistance to second-generation epidermal growth factor receptor gene (EGFR)–tyrosine kinase inhibitors (TKIs)." (PMID 33681226, 2021). "Consistent with a previous report using colon cancer cells, FAM188B knockdown inhibited the growth of lung cancer cell lines regardless of whether they were expressing wild type or mutant EGFR." (PMID 33440835, 2021). "Interestingly, it was recently shown that increased levels of TRIB3 were associated with elevated EGFR stability and signaling activity in lung cancer, suggesting that the disruption of the TRIB3-EGFR interaction could be a novel therapeutic target." (PMID 34198908, 2021). "Adachi and co-workers identified a role for other receptor tyrosine kinases such as EGFR, PDGFRα (platelet-derived growth factor receptor α), and IGFR (insulin-like growth factor receptor) in the emergence of resistance to FGFR inhibitor treatment in FGFR1-amplified lung cancer." (PMID 34830951, 2021). "Hence, our observations of MET dependence in EGFR-mutant lung cancers are unlikely to be an experimental artifact." (PMID 34516823, 2021). "Whether F could be combined with other EGFR-TKIs such as osimertinib to achieve synergy when used with sequential ICB for EGFR-mutant lung cancer has also not been studied." (PMID 35008514, 2021). "EGFR wild-type lung cancer, without evidence of other drivers, also responded to F+D previously, indicating that triple sequential therapy might be effective when the oncogenic driver is unknown." (PMID 35008514, 2021). "Moreover, finding target molecules, such as epidermal growth factor receptor (EGFR), anaplastic lymphoma kinase (ALK), ROS1, and programmed death ligand 1 (PD-L1), is significantly important for making treatment decisions in patients with lung cancer." (PMID 34441366, 2021). "Furthermore, in human lung cancers, HBEGF expression has been positively correlated with levels of EGFR, regardless of EGFR mutational status." (PMID 34494649, 2021). "Thus, paclitaxel-resistant lung cancers are more sensitive to gefitinib and readily undergo apoptotic cell death compared with non-resistant lung cancer, through downregulation of ABCB1, ABCC9, ABCG2, PLK1, and EGFR." (PMID 34503223, 2021). "Insertions in exon 20 (Ex20ins) of epidermal growth factor receptor (EGFR) and human epidermal growth factor receptor 2 (HER2) are relatively insensitive to first‐ and second‐generation EGFR‐tyrosine kinase inhibitors (TKIs) in non‐small cell lung cancer (NSCLC)." (PMID 33210451, 2021). "EGFR and ALK tyrosine kinase inhibitors have demonstrated marked activity in lung cancers harboring driver mutations in these genes; however, these mutations are not driving features of smoking-associated lung cancer." (PMID 33754052, 2021). "In this study, those findings were reproduced using a 3rd lung cancer model that is wild-type to both EGFR and KRAS oncogenes, thereby confirming the wider efficacy of inhaled topotecan against tumors that vary based on the two most common cancer-driver oncogenes in lung cancer." (PMID 33860729, 2021). "The current study demonstrated the LC-C sensitized ionizing radiation-resistant lung cancer cells to radiation both in vitro and in vivo, and the radiosensitization effect was attributed to the up-regulation of ERRFI1 and the down-regulation of EGFR/STAT3 pathway." (PMID 33869036, 2021). "Additionally, EGFR, MGA, SMARCA4, ATM, RBM10 and KDM5C which are lung cancer related genes are mutated only in LUAD but not in LUSC." (PMID 33672117, 2021). "To explore the function of ELF3 in lung cancer, we examined its protein expression in several lung cancer cell lines and found that ELF3 was detectable in most of the cell lines regardless of the mutational status of EGFR or K-RAS." (PMID 34830169, 2021).
lung cancer (continued). "Furthermore, a cationic lipid (DOTAP) was added to the membrane of NLC for non-covalent attachment of the human EGFR siRNA (siGENOME) in order to silence the EGFR gene in lung cancer cells (Step 3)." (PMID 34371754, 2021). "This is critical given that both first-generation EGFR-TKIs gefitinib and erlotinib have since been widely used as second-line or maintenance treatment after chemotherapy failure in advanced non‐small cell lung cancer as opposed to a first-line treatment in chemotherapy-naïve patients." (PMID 33850249, 2021). "Also, RESV appear to reveal antiangiogenic activity in KRAS-mutant lung cancer, but not in EGFR mutant." (PMID 33652978, 2021). "For epithelioid sarcoma cell lines, this might be related to E-CADHERIN re-expression which has been correlated to restore EGFR-TKI sensitivity in epithelial cancers, including both resistant EGFR-mutated and -non-mutated lung cancer." (PMID 34281526, 2021). "In the old lung cancer group, there were genes significantly concurrent with actionable driver genes (CDKN2A, NF1): FAT1, LRP1B, ARID2 with CDKN2A; EPHB1 with NF1, and genes significantly exclusive with actionable driver genes (EGFR, KRAS): MLL2, STK11, KRAS with EGFR." (PMID 35096611, 2021). "Using microvascular endothelial cells, lung cancer derived fibroblasts, and NSCLC tumor cells in the presence of patient tumor-derived hemodynamic flow and transport we demonstrate that the TMES predicts drug response to EGFR inhibitors, a standard of care for EGFR mutant NSCLC." (PMID 33692370, 2021). "In general, EGFR was an important factor in the beginning of lung cancer and then play a decreased role in developed lung cancer and ALK fusions may occur at a later stage in the progression of lung cancer." (PMID 33976731, 2021). "While this work provides fundamental information regarding lineage plasticity in lung cancer, further studies are required to identify novel therapeutic approaches targeting histological trans-differentiation between LUAD and SCLC in the context of EGFR-TKI resistance." (PMID 34121659, 2021). "Thus, the dual targeting of EGFR and MET might be a promising therapeutic strategy to overcome lung cancer that is sensitive or resistant to TKI." (PMID 32070026, 2020). "Osimertinib is a third‐generation, irreversible, oral epidermal growth factor receptor (EGFR)‐tyrosine kinase inhibitor (TKI) that potently and selectively inhibits both EGFR‐TKI sensitizing (EGFRm) and EGFR T790M and has demonstrated efficacy in non‐small cell lung cancer (NSCLC) CNS metastases." (PMID 32567817, 2020). "Based on molecular status, the OS improvement was confirmed for EGFR wild-type lung cancers (OS hazard ratio (HR): 0.67; p < 0.001], but not in those EGFR mutated (OS HR: 1.11; p = 0.54), although no clear conclusions can be drawn due to the limited number of patients as part of subgroup analyses." (PMID 32760402, 2020). "Finally, focusing on the role of tumor microenvironment in c-Src/EGFR regulation, Interleukin 10 (IL10) has been proposed as a cooperative agent in the oncogenic progression of lung cancer by increasing phosphorylation levels of EGFR and c-Src in a dose-dependent manner." (PMID 32517369, 2020). "On the other hand, lack of correlation between EGFR expression and treatment response or survival was reported in 375 tissue specimens in the Tarceva Lung Cancer Investigation Trial, as well as in a cohort of previously treated Squamous cell lung cancer patients." (PMID 33247670, 2020). "Therefore, we further tested whether the inhibition of both the EGFR and the FGFR together attenuates the growth of human lung cancer cells." (PMID 33092268, 2020).
lung cancer (continued). "However, the prognostic value of 18F-FDG PET-based radiomic features for the survival of lung cancer patients treated by EGFR-targeting TKIs has not been well investigated." (PMID 33370365, 2020). "Lung cancer cells with acquired resistance to gefitinib or osimertinib (AZD9291) show EMT characteristics, with a decrease in E-cadherin and an increase in mesenchymal markers and stemness without any EGFR secondary mutations." (PMID 33123465, 2020). "Therefore, EGFR and MET can be attractive targets for lung cancer." (PMID 32070026, 2020). "Interestingly, as opposed to some EGFR mutant lung cancer, CPIs seem to work fairly well in BRAF-mutant melanoma." (PMID 32258034, 2020). "Thus, DYRK1A prevents epidermal growth factor receptor (EGFR) endocytosis-mediated degradation in neural stem cells and indeed, DYRK1A-dependent EGFR stabilization has been described in glioblastoma (GBM) and non–small cell lung cancer (NSCLC) cell lines." (PMID 32751160, 2020). "Enhanced pathway reactivation in CRC relative to melanoma might be suggested as accounting in part for the differences clinically, however combined BRAF/MEK blockade is also highly effective in BRAF mutant lung cancer, a disease which like CRC is characteristically an EGFR expressing cancer." (PMID 32922659, 2020). "We assessed mRNA expression in individual cells isolated from the four lung cancer cell lines, H2228, H460, HCC78, and PC9, and from the blood samples withdrawn from three patients with NSCLC, LP25, LP38, and LP39, before starting their EGFR-TKIs therapy, using WBCs as a control." (PMID 32373206, 2020). "Interrogation of the predicted TK-substrate network generated biologically meaningful hypotheses, followed by experimental validations illustrating the effectiveness of predicted kinase inhibitor combination, EGFR and c-MET combination inhibitors, in treating lung cancer cell lines." (PMID 30615629, 2019). "Using four microsatellite markers that map specific chromosomal loci often lost in lung cancer, we conducted a pilot study to investigate whether other alterations, such as loss of heterozygosity (LOH), could be detected in EGFR-negative cfDNA." (PMID 31861832, 2019). "Regarding KRAS oncogene, despite the fact that KRAS-MAPK pathway is downstream of EGFR signalling, KRAS-mutation-driven lung cancers, which are mostly adenocarcinomas, do not respond to EGFR TKIs because the mutations in KRAS activate and release mutant KRAS from the upstream regulation." (PMID 31795465, 2019). "Given the role of EGFR in lung cancer, we next sought to determine if there was a non-EGFR mutant patient population within lung cancer that could benefit from EGFR inhibition." (PMID 31332182, 2019). "This may partly explain why driver mutations, including EGFR, ALK, and KRAS, were not identified in lung cancer patients." (PMID 31069172, 2019). "Besides, circCDR1as, one of the most frequently studied circRNAs, targets miR-7 in a manner dependent on NF-kB regulatory signaling, upregulates proliferation levels of EGFR, CCNE1, and PIK3CD, and thus induced superior proliferative, migratory, and invasive capabilities of lung cancer cells." (PMID 31534962, 2019). "However, the use of antiangiogenetic drugs and, more in general of targeted therapies, is increasingly growing in advanced diseases, thus resulting in long-term clinical benefit and disease control (e.g., anti-VEGFR and anti-EGFR in colorectal cancer, EGFR TKIs, and ALK inhibitors in lung cancer)." (PMID 31852067, 2019). "Overexpression, activating mutations, and autocrine stimulation of ErbB-family receptors—particularly EGFR and HER2—can lead to uncontrolled cell division via activation of multiple downstream signaling pathways, which is particularly common in breast and lung cancers." (PMID 30671765, 2019).
lung cancer (continued). "Although EGFR was crucial to the proliferation of lung cancer cells, our results suggested that EGFR was not an important target of Ibr‐7 in A549 cells, even considering the intense inhibitory effect of Ibr‐7 on phosphor‐EGFR." (PMID 30663221, 2019). "In other tumor types, such as melanoma, colorectal, and lung cancer, activating BRAF mutations occur mostly in a non-overlapping distribution with other genes that converge on activation of ERK signaling pathways (i.e., KRAS, NRAS, NF1, EGFR)." (PMID 31158244, 2019). "EGFR is an upstream component of the PI3K/mTOR signaling pathway in human neoplasms and is overexpressed in numerous malignant carcinomas (such as breast cancer, gastrointestinal adenocarcinoma, colorectal cancer, and lung cancer) and indicates poor prognosis of cancer." (PMID 30863440, 2019). "In addition, both EGFR and ALK play pivotal roles in lung cancer pathogenesis." (PMID 30634502, 2019). "Although we utilized two NSCLC cell lines with different EGFR status, additional cell lines with different molecular features should be tested to confirm the universality of involvement of the FGFR pathway in the development of pemetrexed resistance in lung cancer." (PMID 30838090, 2019). "For this reason, combinative inhibition of EGFR and IL‐6/STAT3 pathway rather than blockade of EGFR alone might therefore be more effective in the treatment of lung cancer." (PMID 31507089, 2019). "However, the possible roles of p22phox in lung cancer after acquired resistance to EGFR-TKI have not been known." (PMID 30800222, 2019). "Furthermore, the lung cancer cell line Lc2/ad, which carries a RET fusion, shows more resistance to erlotinib compared to SW48 cells, and direct targeting of RET inhibition in Lc2/ad cells can be bypassed by EGFR activation." (PMID 31653970, 2019). "However, this is not conclusive because EGFR mutant lung cancer generally showed better treatment response to EGFR tyrosine kinase inhibitors and survival." (PMID 31389192, 2019). "Because autocrine HGF-MET signaling has been previously shown to play a critical role in lung cancer progression and co-overexpression of HGF with MET is not uncommon, it is attractive to propose targeting HGF-MET also as a potential strategy to curb resistance to EGFR-TKIs." (PMID 31815659, 2019). "Considering that IL-8 signaling has been shown to be fundamentally involved in resistance of lung carcinoma cells to the EGFR TKI erlotinib, our results suggest that IL-8 action on response to EGFR TKIs may be dependent on cell context or types of TKIs-treatments." (PMID 31823748, 2019). "Also, sensitivity of lung cancer cells to EGCG was decreased on knockdown of EGFR, confirming that EGFR signaling may be involved in the anticancer activity of EGCG in human lung cancer cells." (PMID 30585192, 2018). "Among the 2,488 patients who underwent the proteomic test from 2011 to 2013, 257 (10%) of those tested had no lung biopsy or tumor tissue available for EGFR testing, which illustrates the capacity for liquid biopsy tests to improve access to lung cancer molecular testing." (PMID 29554880, 2018). "Various receptor tyrosine kinases such as Epidermal Growth Factor Receptor (EGFR), HGFR/c-Met along with their downstream signalling molecules, such as GRB2, mitogen-activated protein kinase (MAPK), and Phosphoinositide 3-kinase (PI3K), have been found to be over-expressed in lung cancer." (PMID 30087284, 2018). "Lung cancer cell-derived exosomes containing the epidermal growth factor receptor (EGFR) can induce tolerogenic dendritic cells and tumor antigen-specific regulatory T cells (Treg) which can inhibit the function of CD positive T cells with anti-tumor function and promote the growth of lung cancer." (PMID 30217217, 2018). "In addition to oncogenic EGFR and distinct RTKs activated through gene-rearrangements, increased expression of the non-mutated RTK, FGFR1, is observed in lung cancers of all histologies, mesotheliomas and HNSCC." (PMID 29458371, 2018).